RNU6-606P (RNA, U6 small nuclear 606, pseudogene)
Gene: Small nuclear RNA gene on chromosome 5 (87,299,687 to 87,299,797, reverse strand). Ensembl gene ENSG00000207452.
Homologues: Orthologues: chimpanzee U6 (99% identical), macaque U6 (96% identical). Paralogues in human: RNU6-15P (85% identical), RNU6-19P (85% identical), RNU6-1060P (84% identical), RNU6-116P (84% identical), RNU6-211P (84% identical), RNU6-25P (84% identical), RNU6-31P (84% identical), RNU6-41P (84% identical), RNU6-1 (83% identical), RNU6-1152P (83% identical), RNU6-140P (83% identical), RNU6-2 (83% identical), and 1286 more.